INS (insulin)
Diseases named in the same sentence as INS in open-access papers (continued):
Sharing a sentence is not in itself a finding about the gene and the disease.
diabetes (continued). "Insulin-sensitizing therapies such as metformin may exert a threefold effect by lowering the risk of diabetes progression, reducing insulin-mediated ovarian androgen synthesis, and decreasing IGF-1 levels." (PMID 41384021, 2025). "Additionally, certain diabetes therapies can exacerbate muscle loss; for example, metformin induces autophagy in muscle cells, while insulin’s anabolic effects diminish with age." (PMID 39940355, 2025). "In large cohorts, elevated SFA concentrations were declared to have a risk for type-2 diabetes, and a possible mechanism for diabetes was proposed as IR caused by the inhibition of insulin signaling with fetuin-A, and fetuin-A has emerged as a biomarker for diabetes risk." (PMID 40731776, 2025). "In clinical practice, the appearance of rapidly worsening glycemic control, unexpected weight loss, or the need to initiate insulin soon after diabetes diagnosis in individuals aged ≥50–60 years should raise suspicion for occult PDAC and consider further evaluation." (PMID 41597354, 2025). "While insulin can help prevent myocardial infarction (MI), it may also increase the risk of stroke in individuals with diabetes mellitus (DM)." (PMID 41383356, 2025). "Therefore, PTP1B acts as a negative regulator of the IR signaling pathway, as evidenced by studies showing that mice deficient in the PTP1B gene exhibit enhanced insulin sensitivity and a significantly lower risk of developing obesity and diabetes." (PMID 39941054, 2025). "Interestingly, despite being less abundant than Glut4 in adipocytes, Glut1 not only responds to insulin but also to a variety of other stimuli, making this protein less susceptible to the effects of diabetes." (PMID 40825507, 2025). "The hypothesis in this study was that EE may increase the risk of prediabetes and diabetes by increasing insulin resistance or due to decreased insulin secretion." (PMID 40608790, 2025). "Finally, postinjection care practices were significantly associated with duration of diabetes (p = 0.025), insulin therapy duration (p = 0.038), and age (p = 0.029), whereas the type of device again did not have a significant impact (p = 0.078)." (PMID 41306599, 2025). "Type 1 diabetes mellitus, which accounts for 5-10% of cases, is induced by cell-mediated autoimmune defects that lead to the destruction of pancreatic β-cells, resulting in a deficiency in insulin production." (PMID 40391013, 2025). "Although no significant change in FBG was found in human participants after the COVID‐19 mRNA booster shots, 43 of 65 (66.1%) patients with diabetes had impaired insulin sensitivity according to the HOMA‐IR and an increased risk of metabolic dysfunction according to the TyG index." (PMID 41190280, 2025). "Dysregulation of RyRs, whether through increased phosphorylation or the presence of “leaky” channels, impairs insulin secretion, and certain RyR mutations are linked to impaired glucose tolerance and diabetes." (PMID 40422193, 2025). "Despite advancements in insulin formulations and delivery devices, the risk of hypoglycemia remains a significant concern, contributing to both the acute and long-term complications of diabetes." (PMID 41510436, 2025). "Furthermore, consistent physical exercise not only aids in weight management but also improves the body’s insulin sensitivity, thereby promoting stable blood sugar levels and reducing the risk of diabetes." (PMID 40260393, 2025). "By elucidating these mechanisms, researchers may be able to develop novel therapy for treating diabetes caused by INS gene mutations." (PMID 40109403, 2025). "However, many of these studies were performed before the availability of more physiologic insulin analogs associated with reduced hypoglycemia and most before the widespread use of advanced diabetes technologies, specifically hybrid closed-loop (HCL) systems." (PMID 39933614, 2025).
diabetes (continued). "If body fat can be effectively reduced, it can greatly improve metabolic function, increase insulin sensitivity of tissues, reduce the risk of diabetes and heart disease by lowering neutral fat levels, and it is expected to have various effects on promoting health." (PMID 40661686, 2025). "This action is responsible for the inhibition of insulin secretion following cytokine treatment of islets and is the basis for the belief that cytokines participate in, or mediate, the loss of functional β-cell mass during diabetes development." (PMID 40147772, 2025). "Diabetes disrupts multiple metabolic pathways, leading to abnormalities in fat, protein, and carbohydrate metabolism caused by defects in insulin secretion and insulin resistance, resulting in chronic hyperglycemia." (PMID 41383402, 2025). "In non-diabetic populations, low-level alcohol consumption has been hypothesized to improve insulin sensitivity, thereby reducing the risk of diabetes and subsequently lowering the risk of liver cancer." (PMID 40944258, 2025). "In this patient, a history of T2DM managed with insulin may have further contributed, as diabetes is a known risk factor for microvascular complications that can impair blood supply to the femoral head." (PMID 40416257, 2025). "In conclusion, phytochemicals from perilla seed residue lower fasting blood glucose in diabetic rats by enhancing insulin sensitivity via anti-inflammatory effects, protecting β-cells from the oxidative stress caused by a high-fat diet and streptozotocin, and reducing diabetes-related complications." (PMID 40943103, 2025). "A spectrum of mechanisms could account for the inverse association between elevated HDL-C levels and diminished diabetes risk, such as anti-inflammatory responses, enhanced insulin secretion, and augmented glucose uptake by peripheral muscles." (PMID 40444231, 2025). "Given that metabolic disorders such as obesity and diabetes are established risk factors for gallstones, niacin's ability to enhance insulin sensitivity and regulate glucose metabolism may provide an additional protective effect against gallstone development." (PMID 40264748, 2025). "Importantly, patients on insulin tend to have more severe diabetes, making this population more susceptible to other complications." (PMID 41146261, 2025). "Furthermore, pancreatic fat accumulation has been inversely associated with insulin secretion, indicating its potential role in the progression of diabetes." (PMID 40002577, 2025). "The underlying mechanism may involve acute β-cell dysfunction induced by SARS-CoV-2, which contributes to the development of insulin-deficient diabetes." (PMID 40861049, 2025). "Diabetes mellitus (DM) is a chronic and progressive pathological condition that occurs when high blood glucose levels are persistently maintained due to a deficiency in the synthesis of the hormone insulin or significant alterations in its action." (PMID 40218259, 2025). "While diabetes online communities can provide emotional support, individuals can be exposed to a wide variety of diabetes-related information, including risk-taking behaviors, such as alcohol and drug use and inappropriate use of insulin for weight manipulation." (PMID 40599715, 2025). "While some studies report that VD supplementation improves insulin sensitivity and reduces diabetes risk in VD-deficient prediabetic rodents, others have found no significant improvement in β-cell function indices following 24 months of VD3 treatment in prediabetic patients." (PMID 40746531, 2025). "Together, these observations highlight how the most severe metabolic consequences of uncontrolled, insulin-deficient diabetes can be reversed either by convincing the brain that fuel stores are not depleted or by silencing neurons responsible for fuel mobilization." (PMID 40759579, 2025).
diabetes (continued). "It remains unknown whether maternal treatment with pandan and teak extracts influences postnatal metabolic health, including insulin sensitivity, obesity risk, or diabetes predisposition." (PMID 40564970, 2025). "Essentially, the R(B22)Q mutation produces a partially functional insulin molecule that, despite the presence of normal insulin from the other allele, is sufficient to disrupt glucose homeostasis and cause clinically significant diabetes." (PMID 40305339, 2025). "Finally, limitations exist in interpreting the changes in β-cell function and insulin sensitivity around the menopausal period and their relationship with the risk of diabetes as a direct relationship between menopause and diabetes." (PMID 40361840, 2025). "Furthermore, regression analysis indicated that being over 45 years old, male gender, hypertension, coronary artery disease, having diabetes for more than 10 years, insulin use, and hyperlipidemia were independently significant risk factors for stroke." (PMID 41383356, 2025). "Newer diabetes medications that have a lower risk of causing low blood sugar and further benefit cardiovascular and renal outcomes are becoming available in these countries, but their potential implications for insulin use in LMICs are not well understood." (PMID 40245017, 2025). "This assertion is based on the finding that in rodents with uncontrolled insulin-deficient diabetes, leptin action localized to the PBN is sufficient to normalize both glucagon levels and ketogenesis, presumably via projections to the VMN, despite having little effect on hyperglycemia." (PMID 40759579, 2025). "Other contributing factors included the duration of diabetes, which may associate with residual beta-cell function and influence insulin needs." (PMID 41293743, 2025). "In vivo research suggests that increased vegetable intake may help reduce body weight, plasma glucose levels, and insulin resistance, thereby promoting glucose-insulin balance and lowering the risk of diabetes." (PMID 41227672, 2025). "Multivariable linear regression showed that diabetes distress was associated with a 0.2 (95% CI 0.2–0.3) lower score for each year older age, 7.6 (95% CI 5.4–9.7) higher score for current insulin use, and 9.3 (95% CI 5.3–13.2) higher score for a history of diabetes foot ulcers." (PMID 39972441, 2025). "In humans, extensive studies in Ecuadorians with Laron Syndrome (LS), caused by germline inactivating mutations in the GH receptor (GHR), demonstrate improved insulin sensitivity, resistance to diabetes and cancer, enhanced memory function, and decreased pro-aging signaling." (PMID 41350448, 2025). "Diabetes is a metabolic disease caused by a deficiency in insulin levels released from beta cells in the pancreatic islets of Langerhans or changes in the mechanism of insulin action." (PMID 39985597, 2025). "Since the loss of nitrergic myenteric neurons is a hallmark of advanced diabetes, we hypothesize that insulin may help protect nNOS neurons that contain insulin." (PMID 40497986, 2025). "This reveals that mtDNA variants contribute to diabetes pathogenesis through multifaceted mechanisms and thus the need to include not only direct effects on insulin secretion but also broader influences on cellular metabolism in the role of mitochondrial dysfunction in the development of diabetes." (PMID 39835172, 2025). "This review suggests that myonectin may serve as a valuable biomarker to assess the impact of exercise on insulin sensitivity in individuals at risk of diabetes with overweight or obesity." (PMID 40134450, 2025). "These dual effects on both insulin-dependent and insulin-independent glucose regulation pathways underscore the multifaceted therapeutic potential of plant antioxidants in managing metabolic dysfunctions associated with type 2 diabetes mellitus." (PMID 40563357, 2025).
diabetes (continued). "Importantly, after adjusting for insulin therapy, all significant associations disappeared, indicating insulin’s crucial role in modulating the relationship between diabetes and telomere biology." (PMID 40299325, 2025). "Collectively, these findings indicate that HN enhances insulin responsiveness, maintains β-cell integrity, and alleviates mitochondrial stress, underscoring its dual value as a diagnostic biomarker and therapeutic candidate for diabetes." (PMID 41465308, 2025). "Diabetes-related abnormal adipokine secretion and action are associated with dysregulation of several essential processes, including feeding behavior, energy expenditure, insulin sensitivity, reproductive function, and more." (PMID 40806520, 2025). "This phenomenon suggests that insulin therapy may serve as an important effect modifier mediating the phenotypic association between diabetes and TL." (PMID 40299325, 2025). "The higher risk of insulin may be attributed to the fact that insulin is often introduced in advanced diabetes stages, where patients have more comorbidities that independently contribute to poor outcomes." (PMID 40430154, 2025). "It decreases the amount of insulin produced by the pancreas, causing diabetes." (PMID 39859258, 2025). "Studies examining contextual or indirect mechanisms primarily investigated metabolic factors such as insulin sensitivity and diabetes risk, as well as behavioral and psychosocial barriers related to lifestyle modification, physical activity, and cultural adaptation." (PMID 41473668, 2025). "Maturity‐onset diabetes of the young (MODY), a common type of monogenic diabetes caused by a pathogenic variant in a single gene, is characterized by starting at an early age, autosomal dominant inheritance, and decreased secretion of insulin." (PMID 41497485, 2025). "However, logistic EuroSCORE did not include diabetes as a risk factor, whereas EuroSCORE II only included insulin-treated diabetes." (PMID 40810069, 2025). "Notably, they were also more likely to require insulin therapy for diabetes control, placing them at an increased risk of hypoglycaemia." (PMID 39797595, 2025). "Furthermore, the current study found that higher knowledge about insulin use, receiving information about diabetes, and relying on scientific sources for diabetes-related information were significantly associated with better insulin usage practices." (PMID 40471961, 2025). "In the case of the DRRD, a dietary pattern that promotes the intake of multiple healthful components, its association with diabetes reduction may involve multiple metabolic pathways beyond insulin sensitivity." (PMID 40431387, 2025). "Although the specific neuronal cell types are still being identified, leptin receptors are concentrated in this brain area, and microinjection of even a tiny dose of leptin directly into the VMN is sufficient to reverse most manifestations of uncontrolled insulin-deficient diabetes." (PMID 40759579, 2025). "Diabetes mellitus results from the dysfunction and/or loss of insulin-producing β-cells." (PMID 40236756, 2025). "Additionally, a decrease in insulin sensitivity followed by a subsequent decrease in β-cell function depending on the time of onset was related to the risk of diabetes." (PMID 40361840, 2025). "Alpha-blockers effectively target this sympathetic dysregulation, potentially explaining their enhanced protective effect in patients with diabetes by reducing nocturia-related fall risk while simultaneously improving peripheral insulin sensitivity and attenuating orthostatic hypotension." (PMID 40283195, 2025). "Adipokines play a critical role in regulating insulin sensitivity and glucose metabolism, and oral microbiota may interact with these distinct physiological processes, potentially influencing diabetes risk in a manner that differs from the general population." (PMID 40437450, 2025).
diabetes (continued). "What remains unclear is whether such effects translate to insulin-deficient diabetes and, specifically, whether ISO can support β-cell integrity via PI3K/AKT while moderating COX-2/eicosanoid signaling in an integrated manner." (PMID 41156454, 2025). "Interestingly, our study showed no strong CDKAL1 association with the MOD cluster, underscoring the specificity of this gene’s role in insulin-deficient diabetes." (PMID 41422334, 2025). "Determining the cause of death in diabetics is often challenging, especially due to the need to perform an autopsy within a short time after death due to the rapid degradation of relevant biological markers (insulin, glucose, C-peptide, etc.)." (PMID 38965163, 2025). "Diabetes mellitus is a complex, multi-pathway chronic metabolic condition that can be caused by resistance to insulin, insulin-deficiency, autoimmune diseases, dysfunctional pancreatic function, elevated glucose levels, lipids, oxidative stress, and more factors which are still to be determined." (PMID 39858654, 2025). "Against the backdrop of diabetes as a major frailty risk factor, insulin sensitivity could plausibly represent a broadly relevant correlate of slower frailty progression." (PMID 41497955, 2025). "Our study also proved that thiamine supplementation on the basis of intensive insulin treatment can reduce the blood lipids of people with diabetes and reduce the risk of vascular complications in people with diabetes to a certain extent, but the lowering effect on blood sugar is not obvious." (PMID 40299682, 2025). "The wide spectrum of mutations in genes associated with monogenic forms of diabetes results in diverse clinical manifestations, requiring tailored treatment strategies that range from dietary interventions and lifestyle modifications to insulin therapy." (PMID 39859454, 2025). "Previous studies examining diabetes clusters using age at diagnosis, BMI, and C‐peptide showed that Chinese (41%) and Indian populations (27%) had higher proportions of individuals with non‐autoimmune severe insulin‐deficient diabetes compared to the white European population (17.5%)." (PMID 40966384, 2025). "Furthermore, insulin sensitivity decreases within hours of being sedentary, which increases the risk of diabetes with sitting still for a long time." (PMID 40177096, 2025). "In addition to causing dopamine dysfunction, which impairs behavioral and motor regulation, diabetes is associated with glucose fluctuations, the accumulation of advanced glycation end products (AGEs), and brain insulin resistance." (PMID 41450509, 2025). "The impairment of the antioxidant balance in pancreatic β cells with reduced catalase expression and increased concentration of hydrogen peroxide has been associated with reduced insulin production, insulin resistance, and the development of type 2 diabetes mellitus." (PMID 40284576, 2025). "Angiotensin receptor blockers (ARBs) and angiotensin-converting enzyme inhibitors (ACEIs) are commonly prescribed for hypertension, but their differential effects on insulin sensitivity and diabetes risk remain unclear." (PMID 40255834, 2025). "In a reciprocal manner, frailty and pre-frailty increased the risk of incident type 2 diabetes mellitus, which may be due to insulin resistance and glucose dysregulation." (PMID 39852391, 2025). "By reducing insulin requirements and stabilizing glycemic fluctuations, SGLT2i-insulin combination therapy may help mitigate infection risk in patients with diabetes-related complications." (PMID 40863575, 2025). "Specifically, variations in the m6A modification levels of genes implicated in insulin secretion and action could serve as promising biomarkers for the early detection of diabetes." (PMID 40066222, 2025).